ELN (elastin)
Diseases named in the same sentence as ELN in open-access papers (continued):
Sharing a sentence is not in itself a finding about the gene and the disease.
liver fibrosis (31 papers, 2014 to 2024). "Abnormal ELN levels have been observed in many fibrotic diseases, including kidney, lung, and liver fibrosis, and ELN accumulation is associated with the development of hepatocellular carcinoma." (PMID 37061682, 2023). "MMP12 was found to regulate elastin degradation, which was linked to the maturity of liver fibrosis." (PMID 31903104, 2020). "Elastase produced by a subset of hepatic macrophages degrades elastin in the liver and its deficiency leads to enhanced elastin accumulation in experimental liver fibrosis." (PMID 27826254, 2016). "The presence of desmosines, degradation products of elastin, in urine is a potential diagnostic marker of liver fibrosis." (PMID 27826254, 2016). "Liver fibrosis is characterized by increased accumulation of constituents of the hepatic extracellular matrix, including collagen and elastin, which alters the microenvironment and favors cancer initiation and growth." (PMID 38475805, 2024). "Alcoholic hepatitis can lead to liver fibrosis, characterized by the deposition of collagens, elastin, and fibronectin." (PMID 38268900, 2023). "Supportively, LOXs-mediated cross-linking of both collagen and elastin throughout the initiation, progression, and regression of liver fibrosis." (PMID 34367261, 2021). "Liver fibrosis is characterized by an overly abundant accumulation of components of the hepatic extracellular matrix, such as collagen and elastin, with consequences on the properties of this microenvironment and cancer initiation and growth." (PMID 34065048, 2021). "In liver biopsies from patients with chronic hepatitis C, increasing amounts of elastin correlated with the severity of liver fibrosis." (PMID 34065048, 2021). "For example, downregulation of the LOXL1 enzyme led to reduction of collagen and elastin expression alongside decreased elastin cross-linking in the murine CCL4 model of liver fibrosis." (PMID 33498156, 2021). "Nevertheless, elastin turnover is detected in liver fibrosis and cirrhosis, indicated by the presence of elastin fragments in the serum and markers of degradation of mature cross-linked elastin in the urine." (PMID 33262757, 2020). "Elastin is another ECM protein linked to liver fibrosis progression, and macrophage-derived MMP-12 was shown to mediate its degradation during experimental liver fibrosis." (PMID 32296422, 2020). "In two independent studies of Collagen-α1(I)-green fluorescent protein (Col1a1GFP) mice with induced liver fibrosis, Fibulin 2, Thy-1 and elastin were overexpressed in cells considered as activated portal fibroblasts." (PMID 27065888, 2016). "This is also the case for elastin, a marker of maturity of liver fibrosis that was logically up regulated in HSC as compared to ADHLSC." (PMID 24516514, 2014). "Irreversible liver fibrosis is caused by non-reductive crosslinking of elastin and collagen fibers, a process mediated by proteins of the LOX family." (PMID 39108737, 2024). "Moreover, MFAP4, together with TE, participates in the assembly of elastin and the two proteins are upregulated in liver fibrosis and cirrhosis, and can serve as a biomarker of liver fibrosis." (PMID 34798886, 2021). "Non-invasive assessment of elastin or collagen in liver fibrosis may be visualized by MRI-based methods." (PMID 34055744, 2021). "In fibrosis imaging, non-invasive assessment of Collagen and Elastin might in future enable significantly improved and more specific assessment of liver fibrosis." (PMID 31635053, 2019). "Elastin is also found in the liver and is present a higher density in liver fibrosis and cirrhosis, making it a potentially useful biomarker of the severity of liver fibrosis." (PMID 27121383, 2016). "The regulation of liver elastin synthesis and degradation may be important for the outcome of liver fibrosis." (PMID 27826254, 2016).
liver fibrosis (continued). "Several reports implicate LOXL2 in ECM buildup and stabilization during liver fibrosis through crosslinking of structural proteins such as type I and III collagens and elastin." (PMID 32296422, 2020). "As expected, liver fibrosis evolution from F1 to F3 stages requires a progressive accumulation of fibrillar collagen (type I and III) and elastin." (PMID 26998606, 2016). "For instance, MRI-based imaging of liver fibrosis can be enabled by visualizing fibrosis based on non-invasive analysis of collagen or elastin." (PMID 31635053, 2019). "Elastin is a type of noncollagenous protein found in the ECM that is secreted by HSCs; it is also associated with the stage of liver fibrosis." (PMID 25874221, 2015). "Examples were represented by elastin fragments in the serum of fibrotic and cirrhotic patients, the correlation of LAM-P1 serum level with the degree of fibrosis progression and inflammation in ALD and NAFLD patients, and the high levels of biglycan in the serum of rat models of liver fibrosis." (PMID 33262757, 2020). "The feasibility of monitoring ECMs with ESMA, the elastin-specific MR contrast agent, has previously been assessed, and the study findings suggested that elastin-based molecular MRI has potential as a noninvasive method for monitoring ECM remodeling during liver fibrosis." (PMID 25874221, 2015). "In the normal liver, elastin is a minor component of the ECM, but tropoelastin is actively synthesised by hepatic myofibroblasts in liver fibrosis regardless of the aetiology." (PMID 33262757, 2020).
Obesity (30 papers, 2011 to 2025). Accumulation of substantial excess body fat. "Evidence suggests that the polymorphism of the matrix metalloproteinase gene is linked to the susceptibility of obesity by affecting the remodeling of adipose tissue and to the risk of myopia by influencing the synthesis of scleral elastin." (PMID 39861390, 2025). "A number of studies suggest that obesity is associated with increased elastase activity leading to elevated plasma levels of elastin-derived peptides that in turn bind to their receptor and increase neuraminidase activity." (PMID 27458385, 2016). "Our finding that mild obesity may already damage elastic fibers to a point where they become more susceptible to degradation by baseline NEP activity may partly explain why elastin loss and skin sagging persist even after significant weight reduction." (PMID 40806842, 2025). "It is believed that obesity could be a risk factor for development of KC in predisposed people and this might occur due to decreased tarsal elastin, which leads to laxity of palpebral skin, changes palpebral function, and provides corneal irritation." (PMID 37460969, 2023). "In the setting of WD‐induced obesity, elevated blood pressure has also been implicated in increased arterial stiffness via increases in pulse pressure and pulsatile aortic wall stress that can accelerate elastin degradation." (PMID 35561022, 2022). "However, the role of elastin and fibrillin-1 in obesity and obesity-associated cancer progression remains to be investigated." (PMID 36428776, 2022). "PPARγ activation directly upregulated CTSS and MMP-12 expression in the cell types within the PVAT and aorta, accompanied by a reversal of elastin fiber fragmentation and a reduction of elastolytic activity in obesity." (PMID 33781257, 2021). "The improvement of PVAT and the local microenvironment surrounding the artery by pioglitazone in obesity further contributed to the attenuation of elastin fiber fragmentation, elastolytic activity, and expression of elastic fiber degradation enzymes." (PMID 33781257, 2021). "Pioglitazone treatment attenuated obesity-induced elastin fiber fragmentation and elastolytic activity and ameliorated the obesity-induced upregulation of cathepsin S and metalloproteinase 12, predominantly in the PVAT." (PMID 33781257, 2021). "The relative levels of collagen and elastin determine biomechanical properties of vessels, and the increase in collagen/elastin ratio observed in different models of obesity therefore leads to increased stiffness." (PMID 33800427, 2021). "To continue investigating the role of elastin in metabolic and obesity pathology, we performed qPCR analysis of key elastic fiber assembly and degradation-associated genes." (PMID 26167199, 2014). "A previous study proposed that obesity might decrease elastin in the tarsal plate, which leads to weaker eyelid skin and in turn decreases eyelid function in protecting the cornea." (PMID 37853356, 2023). "Obesity may lead to reduced eyelids and elastin, and when eye rubbing occurs, it will aggravate the damage to the cornea from eye rubbing." (PMID 37853356, 2023). "The activation of NEU-1 is required for elastogenesis and signal transduction through this receptor, and this is responsible for the biological effects that are mediated by the elastin-derived peptides (EDP) on obesity, insulin resistance and non-alcoholic fatty liver diseases." (PMID 36230790, 2022). "Although no changes in elastin levels is associated with obesity, there has been reported a reduction in fenestra number in the internal elastic lamina in mesenteric arteries from obese mice." (PMID 33800427, 2021). "Similar to COL6, elastin deposition is increased in VAT depots with obesity." (PMID 32283761, 2020). "Because of the upregulation of MMPs in obesity, a decrease in elastin is observed in obese WAT." (PMID 31581657, 2019).
Obesity (continued). "This suggests that elastin production and accumulation in blood vessels in obesity varies according to the characteristics of the obesity-inducing stimulus, the time of stimulation and the vascular bed analyzed, with an apparent preference for greater elastin deposition in resistance vessels." (PMID 27458385, 2016). "Interestingly, differences in the amount of signal for production of elastin in response to diverse dietary interventions to induce obesity varies between vascular beds." (PMID 27458385, 2016). "Furthermore, as obesity has been shown to alter collagen and elastin expression in adipose tissue, it would be important to examine the influence of CR on collagen metabolism in future." (PMID 22748184, 2012). "Therefore, the observed upregulation of ELN in mild obesity may reflect a compensatory response to early tissue stress." (PMID 40806842, 2025). "This may help explain why elastic fiber loss can occur in mild obesity despite the absence of significant increases in the expression of elastin-degrading enzymes." (PMID 40806842, 2025). "Through scRNA-seq analysis of HFD stromal fibroblasts relative to RD counterparts, we found that obesity promoted stromal fibroblasts to express ECM proteins (e.g., collagen, elastin, and glycoprotein)." (PMID 32785175, 2020). "Of significant interest are the mechanisms that initiate remodeling of the ECM within the microvasculature, specifically what changes the equilibrium of elastin synthesis/degradation to favor increased elastin deposition and IEL remodeling in WD-induced obesity?" (PMID 27458385, 2016). "Our current study suggests that the transcriptional regulation of elastin-degrading enzymes may not be markedly affected by modest increases in the BMI and may only become evident at more advanced stages of obesity." (PMID 40806842, 2025). "The pathophysiology explaining the correlation of KC with obesity is not entirely understood, but it is hypothesized that obesity leads to weaker eyelid skin due to decreased elastin in the tarsal plate." (PMID 39556086, 2024). "Obesity drives an excessive lipid accumulation in adipocytes, which provokes immune cells infiltration, fibrosis (an excess of deposition of ECM components such as collagens, elastin, and fibronectin) and inflammation, considered a consequence of local hypoxia, and ultimately insulin resistance." (PMID 31581657, 2019). "While our animals did not gain weight over the treatment period, our data are the first to demonstrate that high‐fat diet per se, even independent of obesity, induces structural maladaptations in the arterial wall; notably, reduced elastin content of the medial layer." (PMID 24760522, 2014).
breast carcinoma (23 papers, 2003 to 2025). "Given the significance of the extracellular matrix and associated proteins within our tryptic digest, a subsequent elastase digest was performed to target elastin, which has been associated with breast cancer invasion." (PMID 38928454, 2024). "Ctsl, highly expressed in lung cancer, breast cancer, and glioma, is implicated in the synthesis of elastin, collagen, and α-1 protease inhibitors, all of which are crucial for tumor progression." (PMID 39161591, 2024). "An immunochemical study assessed the expression of elastin and MMPs-2, -4, and -9 in a murine model of pulmonary breast cancer metastasis, that showed the degradation of elastin is associated with an increased expression of these MMPs in lungs in the phases of micro- and macro-metastasis." (PMID 33418894, 2021). "Highly expressed PTN strikingly increased the synthesis of collagen and elastin in breast cancer derived from MMTV-PyMT transgenic mice, but the detailed mechanism was unclear." (PMID 40069574, 2025). "Elastosis, rarely observed in breast cancers, is a condition in which degradation products of elastin fibers, one of the fiber components, accumulate in the tumor." (PMID 40013205, 2025). "In our study, we constructed and validated an ECM signature consisting of the expression of fibrinogen, elastin, fibronectin, and vitronectin to effectively predict clinical outcomes in patients with breast cancer." (PMID 37369642, 2023). "We further established an ECM signature based on the fibrinogen/fibronectin/vitronectin/elastin axis, which efficiently predicts patient prognosis in breast cancer." (PMID 37369642, 2023). "ELN is a crucial element of the extracellular matrix that promotes breast cancer progression by enhancing the activation of matrix metalloproteinases (MMPs) but is scarcely documented in BLCA." (PMID 36973787, 2023). "The expression data of ECM fiber-encoding genes (e.g., COL1A1, COL1A2, FGA, FGB, FGG, ELN, FN1, and VTN) from 1358 patients with breast cancer were used for Kaplan–Meier overall survival analysis." (PMID 37369642, 2023). "Pulmonary parenchyma containing collagen and elastin fibers acts as a favorable environment for homing of breast cancer expressing VCAM-1." (PMID 33418894, 2021). "Previous studies have shown that ELN promotes human breast cancer cell invasiveness, indicating a potential role of ELN in cancer cell migration." (PMID 32171282, 2020). "Breast cancer elastosis is a complex phenomenon resulting in both the deposition of elastotic masses and the local production of elastin fragments." (PMID 30186741, 2018). "What is the biological significance of aggregation of large quantities of elastin fibres in breast cancer stroma?" (PMID 25522915, 2014). "In breast cancer, elastin is observed as both individual fibres in the stroma and large aggregates around ducts or small blood vessels." (PMID 25522915, 2014). "Both histochemical and molecular studies of breast cancer stroma have been conducted, and one striking finding in many tumours is the large aggregates of elastin fibres, known as elastosis." (PMID 25522915, 2014). "A tumour stroma rich in elastin fibre aggregates (elastosis) is a frequent finding in breast cancer." (PMID 25522915, 2014). "Expression of elastin (gene U77846) in breast carcinoma cells has been demonstrated by immunohistochemistry and in situ hybridization." (PMID 17316436, 2007). "Regarding elastin, it is worth mentioning that elastosis, which results from an abnormal increase in expression of the components of elastin fibers and excessive degradation of normal elastic fibers, is a common feature in breast cancer." (PMID 35268340, 2022). "Another example is breast cancer, where elastin promotes the invasiveness of breast cancer cells." (PMID 34827210, 2021). "Some elastin-related effects may be mediated by elafin, an inhibitor of elastase, which recently has been shown to be a positive prognostic factor in breast cancer." (PMID 25522915, 2014).
breast carcinoma (continued). "Our results further suggest that the roles of elastin and collagen may be distinct, further mechanistic studies are needed to explore their specific functions in the initiation, progression, metastasis, and treatment of breast cancer." (PMID 39744437, 2025). "Since the serine protease PMN-E is the only neutral protease that is able to degrade insoluble elastin, which is a structural component of breast tissues, we considered it of interest to study the clinical relevance of PMN-E in breast cancer." (PMID 12671709, 2003). "Elastin-based hydrogels, formed by elastin-like recombinamers (ELRs), have demonstrated high viability and cell proliferation for up to 7 days when cultured with breast cancer or non-tumorigenic breast cells." (PMID 38102637, 2023). "Next, we showed hypoxia enhanced breast cancer cell migration, and expression and secretion of lysyl oxidase (LOX), which is copper-dependent amine oxidase and has the primary function to drive the crosslinking of collagen and elastin and is regulated by hypoxia." (PMID 30181809, 2018).